MTOR (mechanistic target of rapamycin kinase)
Diseases named in the same sentence as MTOR in open-access papers (continued):
Sharing a sentence is not in itself a finding about the gene and the disease.
tumor (continued). "The suppression of the PI3K/AKT/mTOR signaling pathway can induce autophagy, which in turn saves tumor cells from the harm of epidermal growth factor receptor (EGFR)-tyrosine kinase inhibitors (TKIs)." (PMID 34336650, 2021). "PI3K/AKT/mTOR pathway plays a key role in cell proliferation, survival, cell motility, cellular metabolism and cell cycle in various tumor types." (PMID 35201437, 2021). "Research has ascertained the involvement of suppression of the EGFR/PI3K/Akt/mTOR signaling pathway in the oxymatrine-mediated anti-tumor effects on GBM cells." (PMID 33768139, 2021). "Conversely, decreased glucose concentrations following enhanced glucose consumption by tumor cells result in downregulation of mTOR activity in antitumor immune cells, glycolysis, and chemokine secretion." (PMID 35250965, 2021). "Out results indicated that miR-496/LYN inhibited the tumor growth by suppressing the AKT/mTOR signaling pathway." (PMID 34514167, 2021). "Phosphatase and tensin homolog (PTEN) (OMIM 601728) is a tumor suppressor negatively regulates Phosphoinositide 3‐kinase/AKT/mammalian target of rapamycin (PI3K/AKT/mTOR) pathway that plays an important role in cell growth, survival, and proliferation." (PMID 34268892, 2021). "Its induction in endothelial cells has been shown to suppress tumor angiogenesis via reduction of mTOR-mediated phosphorylation and activation of STAT3 and resulting VEGFa expression." (PMID 34128833, 2021). "It makes the tumor addicted to specific amino acids and in turn to mTOR signaling, which can be treated by certain existing therapies." (PMID 33921282, 2021). "AKT/mTOR signaling pathway has also been used to investigate the synergistic use of PTX in anticancer mechanisms and confirm that the regulation of AKT/mTOR pathway is expected to address the issues with PTX anti-tumor resistance." (PMID 34584572, 2021). "The effect of different drugs with the ability to block tumor metabolism has been studied in breast cancer, such as the combination of metformin and oxamate, mTOR, and LDH-A inhibition, leading to apoptosis and autophagy activation." (PMID 34692471, 2021). "It has been reported that EPHA2 promotes malignant tumor progression by enhancing the AKT/mTOR signaling pathway." (PMID 33834064, 2021). "Mutations in this gene have been shown to be strongly associated with tumor development, through activation of the PI3K/mTOR pathway." (PMID 34680390, 2021). "Based on an increasing number of studies, the AMPK/mTOR signaling pathway plays a vital role in tumor proliferation and metastasis." (PMID 33816275, 2021). "Here, we identified effective protection against PDAC by puerarin and showed that the Akt/mTOR signaling pathway played an important role in the anti-tumor effect of puerarin." (PMID 34863080, 2021). "The gain on 1p36.22 corresponds to the mTOR gene, which promotes proliferation of the cell, acceleration of its metabolism, contributes to tumor progression and downregulates autophagy." (PMID 34063545, 2021). "Western blots from the xenograft tumor tissues confirmed that temsirolimus is highly effective at inhibiting mTOR and S6K1 phosphorylation in vivo." (PMID 33479203, 2021). "We also examined the effects of the drug treatments on mTOR signaling in vivo, through analysis of tumors by immunohistochemistry (IHC), and immunoblotting of tumor lysates." (PMID 33891611, 2021). "Due to mTOR's action on tumor cell growth, vascular smooth muscle cells, and hypoxia‐inducible factor synthesis, the desired effect of mTOR inhibition is the suppression of tumor cell proliferation and inhibition of angiogenesis, even under hypoxic conditions." (PMID 33638305, 2021).
tumor (continued). "mTOR signaling mainly regulates cell proliferation and the metabolism involved in tumor initiation and progression." (PMID 33802643, 2021). "Analysis of genetic screen data reveals that, in normoxia, HIF1A behaves as a strong tumor suppressor, which is genetically linked to its target DDIT4, a repressor of mTOR signaling." (PMID 33654095, 2021). "We examined mTOR signaling, tumor cell growth, colony formation, apoptosis, senescence, oxidative stress, p21 accumulation and endoplasmic reticulum (ER) stress levels in cells treated with MHY1485 and radiation, either alone or together." (PMID 34265852, 2021). "The failure to activate the PI3K/Akt/mTOR-mediated death process, including apoptosis or autophagic death, is a major mode of drug resistance in tumor cells." (PMID 34046349, 2021). "A large body of evidence also indicates a deleterious influence of aberrant mTOR signaling in the central nervous system upon cognition, in addition to its tumor growth promoting effects." (PMID 34576341, 2021). "Phosphatase and tensin homolog on chromosome 10 (PTEN) is known as a powerful tumor suppressor and frequently mutated in lung cancer and is the negative regulation of the PI3K/mTOR/AKT oncogenic signaling pathway." (PMID 33796457, 2021). "One AMPK tumor-suppressive functions is hindering the synthesis of most cellular macromolecules by deactivating the mTOR signalling pathway." (PMID 34451875, 2021). "Protracted interruption of mTOR inhibitor treatment in TSC often leads to tumour regrowth or seizure worsening." (PMID 34632383, 2021). "The regulation of xCT activity in tumor cells via mTOR inhibition in this study can be supported by recently published studies." (PMID 33959512, 2021). "The TSC1/TSC2 complex is the main upstream regulator of mTOR, and hyperactivated mTOR, caused by the loss of TSC1 or TSC2, leads to uncontrolled cell proliferation and tumor growth." (PMID 34341336, 2021). "miR-3182 down-regulation was associated with up-regulation of genes involving several vital signaling pathways in carcinogenesis and tumor metastasis, including mTOR and MMP2." (PMID 33882454, 2021). "The mTOR inhibitors which were used as a monotherapy for HNSCC improved the partial tumor response in patients that failed in chemotherapy and/or radiation therapy." (PMID 33802643, 2021). "According to these data, we can infer that Notch signaling and mTOR signaling axis are key players in modulating cellular metabolism and tumor growth during brain metastasis." (PMID 35071325, 2021). "This contrasts with leucine, of which HMB is a metabolite, which promotes tumor growth and mTOR activation in PDAC." (PMID 34944981, 2021). "HOTAIR also activated the mTOR pathway via regulating miR-125a, resulting in increased tumor viability." (PMID 34322395, 2021). "The PI3K/AKT/mammalian target of rapamycin (mTOR) pathways are frequently responsible for uncontrolled tumor cell growth and drug resistance in BC." (PMID 34829916, 2021). "In a study on the application of cisplatin and a mammalian target of rapamycin (mTOR) inhibitor, invasion and migration of tumour cells was drastically impaired." (PMID 34344453, 2021). "Genetic screen data indicates that, in normoxia, HIF1A displays strong cell-autonomous tumor suppressive effects through a gene module mediating mTOR inhibition." (PMID 33654095, 2021). "Overall, these results demonstrate that rhein effectively inhibits CRC tumor growth through the mTOR pathway in vivo and has potential as a chemotherapeutic agent for CRC." (PMID 33946531, 2021). "The western blotting assays of tumor tissue lysates showed that TSN inhibited the PI3K/Akt/mTOR signaling pathway and the expression of MMP-2, cyclin D1, and Bcl-2 proteins." (PMID 34530814, 2021). "In summary, we identified CSNK2B as an oncogene in CRC, which promotes tumor cell proliferation in vitro and in vivo by activating the mTOR signaling pathway." (PMID 33928514, 2021).
tumor (continued). "GH is also implicated in tumor growth, altering regulation of the phosphoinositide-3-kinase–protein kinase B/Akt (PI3K/AKT) pathway, which leads to increased activation of mammalian target of rapamycin (mTOR)." (PMID 33713207, 2021). "Studies have reported that mTOR inhibitors achieve an increasing anti-tumor effect when combined with other drugs such as anti-osteoporotic drugs, extra-terminal domain protein inhibitors, and conventional ChT drugs." (PMID 33467481, 2021). "Based on our findings, a therapy with the mTOR inhibitor everolimus in combination with tamoxifen was recommended to the patient when a progress of the tumor was observed under therapy with palbociclib and fulvestrant at T31." (PMID 34885114, 2021). "Previously, Chen and colleagues also reported that the inhibition of PI3K/Akt/mTOR signaling results in decreased CCSCs proliferation and leads to the suppression of xenograft tumor growth." (PMID 34206937, 2021). "PI3K/AKT/mTOR signalling pathway inhibitors have a more durable effect on the normalization of tumour blood vessels than of traditional anti‐angiogenic drugs." (PMID 34120414, 2021). "An intriguing link between mTOR and Wnt pathways is the mTOR complex protein Deptor that has been shown to be a tumor promoter in CRC and a downstream target of canonical Wnt and c-Myc signaling." (PMID 33668092, 2021). "The ability of tumor cells under nutrient and stress conditions to inhibit mTOR signaling and reducing protein synthesis to conserve energy is well documented." (PMID 33868588, 2021). "Nicardipine can inhibit autophagy by activating expression of mTOR, thus play tumor inhibition roles both in vitro and in vivo." (PMID 33621205, 2021). "In tumour cells, however, abnormally activated mTOR sends signals that encourage tumour cells growth, metastasis, and invasion." (PMID 33923883, 2021). "Blockade of the pathway with mTOR inhibitor sirolimus not only inhibits tumor growth but also suppresses the T cell infiltration in colitic lesions." (PMID 34987517, 2021). "Consistent with the reduced SPAG5 protein levels induced by FeSiNTs-siSPAG5, western blotting showed significantly decreased expression of PI3K/AKT/mTOR signaling pathway members in the tumor mass." (PMID 34162370, 2021). "HAGLROS inhibits apoptosis and promotes autophagy to regulate tumor biological behavior mainly via the PI3K/AKT/mTOR and miR-100/ATG5 pathways." (PMID 34692467, 2021). "S-palmitoylation of PD-1 in tumour cells can modulate downstream mammalian target of rapamycin (mTOR) signalling and proliferation." (PMID 33653086, 2021). "Our findings on the combined effect of ICI and mTOR inhibitors on the SC31 model further support the case for estrogen-related effects on ESR1– cells in this tumor model." (PMID 34944995, 2021). "Concerning metastatic tumours, conventional therapeutic methods such as multitarget tyrosine kinase inhibitors (TKIs) and mammalian target of rapamycin (mTOR) inhibitors are extensively adopted; however, the therapeutic benefits are modest." (PMID 34281531, 2021). "A recent study proved that inhibition of the PI3K/Akt/mTOR pathways resulted in diminished stem cell characteristics of PC and tumor advancement." (PMID 33946266, 2021). "In contrast to modulating the PI3K/AKT/mTOR pathway, we reveal PTEN loss drives a transcriptional axis centered on PAX7 necessary for FN-RMS tumor identity." (PMID 34535684, 2021). "Further, curcumin down-regulates Akt/mTOR through upregulation of autophagy and finally, curcumin inhibits tumor weight and volume in vivo." (PMID 34402718, 2021). "We identified a novel anti-tumor function of bupivacaine in NSCLC progression by activating autophagy through inhibiting Akt/mTOR signaling." (PMID 33777755, 2021). "Histological type, tumor grade, PTEN loss and the expression of molecular markers of the PI3K/Akt/mTOR pathway (mTOR, phosphorylated AKT (pAKT) and phosphorylated S6 (pS6)) did not correlate with the clinical outcome." (PMID 34944775, 2021).
tumor (continued). "Many studies have reported that the AMPK/mTOR signalling pathway is involved in the regulation of tumour metabolism." (PMID 34926459, 2021). "As an mTOR inhibitor, sirolimus can activate autophagy, but it has been reported that autophagy is activated in UC and correlated with tumor progression." (PMID 35071023, 2021). "A large number of studies have found that oncogenes activate mTOR‐related pathways to promote tumor metastasis by inhibiting autophagy." (PMID 34977870, 2021). "Aberrant regulation of PI3K/AKT/mTOR pathway provides a proliferative advantage to tumor cells and it contributes to drug resistance development." (PMID 33923896, 2021). "AKT1 is a well known protein kinase that plays an important role in carcinogenesis by triggering tumor progression via the mammalian target of rapamycin (mTOR) signaling pathway." (PMID 34531452, 2021). "In abnormally activated mTOR tumor cells, it sends growth, metastasis, and invasion signals to other tissues." (PMID 34604242, 2021). "Amino acid uptake regulates the intracellular glutathione (GSH) levels, endoplasmic reticulum stress, unfolded protein response signaling, mTOR-mediated antioxidant defense, and epigenetic adaptations of tumor cells to oxidative stress." (PMID 33401748, 2021). "The treatment with MEL of tumor bearing rats during 60 days led to a decrease in tumor size that was related to reduced levels of mTOR." (PMID 33440795, 2021). "Several studies have proved that PI3K/AKT/mTOR pathway and Hh pathway interact with each other for tumor metastasis enhancement by induction of epithelial-mesenchymal transition (EMT)." (PMID 34203598, 2021). "Nutrient restriction within the tumor microenvironment dampens the activity of mTOR, an essential factor for the activity of potentially infiltrating CD8+ T lymphocytes." (PMID 34504486, 2021). "PTEN is a phosphatase which directly blocks the activation of oncogenic phosphatidyl inositol 3-kinase/protein kinase B/mammalian target of rapamycin (PI3K/AKT/mTOR) signaling pathway, thus serving as an important tumor suppressor." (PMID 34796092, 2021). "A combination of PD-1 blockade with Akt-mTOR inhibition reduced the tumor growth, accompanied by a decrease in Foxp+ Treg cells and an increase in CD3+ T cells, indicating immune activation." (PMID 34163519, 2021). "The PI3K/AKT/mTOR pathway is abnormally activated in a variety of tumor cells, regulating tumor occurrence, development, drug resistance, and the Warburg effect." (PMID 33849427, 2021). "First, we compared the protein expression of mTOR and p-mTOR between three cases of ccRCC and their adjacent non-tumor specimens." (PMID 34458019, 2021). "The expression of the additional markers (AKT, SRC, mTOR, NF-κB, Ki-67) are clues for the aggressiveness of the tumor." (PMID 33313992, 2021). "Metformin had anticancer effects including mTOR pathway blockade leading to downregulation of neovascularization, tumor cell apoptosis induction at the mitochondrial level, and inhibition of epithelial-to-mesenchymal transition." (PMID 34208926, 2021). "Our results indicate that autophagy was activated in tumor cells and suggest that taxifolin-induced inhibition of mTOR increased autophagy activity in vivo." (PMID 34462635, 2021). "Alternatively, inhibition of the immunosuppressive effect of mTOR inhibitors represents another treatment option that has already been validated in tumor vaccine experimental settings." (PMID 33802831, 2021). "The PI3K/Akt/mTOR pathway regulates protein synthesis, tumor growth, metastasis, EMT-TFs, and the EMT program." (PMID 33462219, 2021). "Inhibition of AKT/mTOR signaling promotes autophagy and sensitizes tumor cells to anticancer drugs by reducing cell growth, cell cycle, cell survival, differentiation, and metabolism." (PMID 34017854, 2021). "OGFRP1 promoted tumor progression by increasing the activity of the AKT/mTOR pathway or directly interacting with miR-4640-5p." (PMID 34987577, 2021).
tumor (continued). "The results of the combined analysis of IL-6 and tyrosine kinase inhibitors (TKI) showed that high levels of IL-6 can upregulate the mTOR signaling pathway and induce tumor cell resistance to TKI therapy." (PMID 33582655, 2021). "Abnormal activation of the mTOR signaling pathway is correlated with the progression of different tumor types including CRC." (PMID 33928514, 2021). "Within the TME, tumor cells outcompete T cells for glucose, leading to sustained mTOR signaling and glycolysis in the tumor cells and, consequently, tumor progression." (PMID 35250965, 2021). "Activated PI3K can convert phosphatidylinositol biphosphate (PIP2) into phosphatidylinositol triphosphate (PIP3), which subsequently activates AKT/mTOR pathway and drives tumor proliferation and progression." (PMID 33874915, 2021). "Combinational treatment of mTOR (AZD8055) with either MEK (trametinib) or BRD4 (JQ1) inhibitors to EIF1AX-A113splice knock-in tumour cell lines result in reduced c-MYC and mTOR protein levels and consequent tumour size reduction." (PMID 34062862, 2021). "The inhibition of mTOR complex can be a strategy for the development of new therapies against neoplasms since it would inhibit cell proliferation and induce apoptosis." (PMID 33668689, 2021). "P-PI3K p85 (Tyr607), p-AKT (Ser473), and p-mTOR (Ser2448) have been shown to be related to the biological behavior of tumor cells." (PMID 34823532, 2021). "We then analyzed the relationship between these three clusters and the clinicopathological characteristics of KIRC patients, and the results showed that T (tumor), M (metastasis), stage, grade, and fustat, were related to the mTOR pathway." (PMID 34194607, 2021). "While examining the mRNA levels of several key regulators of oncogenic signalling pathways, including Ras/Raf/Mapk, PI3K/AKT/mTOR and Wnt signalling, we found 5, 9 and 15 differentially expressed genes respectively between tumor of WT and KO." (PMID 34685767, 2021). "The PI3K/AKT/mTOR signaling pathway plays an important role in regulating tumor cell proliferation, metastasis, apoptosis, and other physiological functions." (PMID 34046349, 2021). "Signals from aberrantly activated mTOR not only promote the growth and metastasis of tumor cells but also help the cells invade healthy tissues." (PMID 33925400, 2021). "PI3K/Akt/mTOR signaling was involved in multiple pathways and played a vital role in proliferation, migration and angiogenesis of tumor cells." (PMID 34837694, 2021). "These tumor cells with reduced mTOR activity demonstrated greater resistance to treatment with palbociclib than tumor cells from mTOR wild-type mice." (PMID 34439268, 2021). "Recently, we have demonstrated that para-toluenesulfonamide is a potential anti-tumor agent in human castration-resistant prostate cancer (CRPC) through inhibition of Akt/mTOR/p70S6 kinase pathway and lipid raft disruption." (PMID 34641511, 2021). "ccRCC is recognized as one of the more responsive tumors to immunotherapy, and mTOR has been reported to be participate in tumor immunity (Posadas, Limvorasak & Figlin, 2017; Saxton & Sabatini, 2017)." (PMID 34458019, 2021). "Competition for cellular metabolic nutrients (glucose and amino acids) between T cells and tumor cells within the tumor microenvironment can diminish T cells mTOR activity, glycolytic capacity, and cytokine release." (PMID 34830929, 2021). "SIRT1 also can promote tumor cell growth with autophagy activity that requires mTOR inhibition, suggesting that both SIRT1 and autophagy pathways can be targets to control tumor cell growth." (PMID 34356626, 2021). "The Akt/mTOR pathway has been widely studied in various tumor cells, with its role in OS attracting considerable attention." (PMID 34584572, 2021). "This study analyzed blood samples of patients with predominant clear cell mRCC who were treated with the mTOR inhibitor everolimus after failure of one prior tumor therapy." (PMID 34070677, 2021).